PPARA (peroxisome proliferator activated receptor alpha)
Diseases named in the same sentence as PPARA in open-access papers (continued):
Sharing a sentence is not in itself a finding about the gene and the disease.
cancer (continued). "Furthermore, a study has demonstrated the immunosuppressive role of PPARα in cancer, with TDEs containing long-chain fatty acids, increasing lipid content in DCs via PPARα activation, suggesting the potential for DC-based cancer therapy." (PMID 39327610, 2024). "In many cancer cell lines, fatty acids delivered by TDEs can be induced by PPARα to lead to excessive lipid droplet production, enhance fatty acid oxidation and drive DC immune dysfunction by shifting the metabolic model to mitochondrial oxidative phosphorylation." (PMID 38245525, 2024). "The role of PPARα and PPARβ/δ in cancer cell proliferation is more controversial." (PMID 36834531, 2023). "In terms of cancer promotion, CSCs, as the starting cell population of tumor tissue, exhibit similar self-renewal and differentiation characteristics to normal stem cells and significant upregulation of PPARα, and are important in energy metabolism." (PMID 37251321, 2023). "PPARA is a transcription factor, and it can modulate lipid, glucose, and amino acid metabolism, regulate inflammation, and display a tumor suppressor or oncogene role in many cancer types." (PMID 37201027, 2023). "Summary of the application of PPARα-targeting drugs in cancer therapy." (PMID 37251321, 2023). "Additionally, in PAAD and CRC, the PPARα signaling pathway ensures high lipid turnover in cancer stem cells, maintaining their high energy requirements and self-renewal." (PMID 38189049, 2023). "Our group has previously identified a family of sulfonimide and amide derivatives as selective and potent PPARα antagonists, displaying marked antiproliferative effects in the low micromolar range on several cancer cell lines (pancreatic, colorectal, and paraganglioma models)." (PMID 36674831, 2023). "In addition to the lipid-lowering effects, drugs targeting PPARα also have therapeutic effects in cancer." (PMID 37089950, 2023). "PPARα has a similar cancer-promoting effect in cancer stem cells." (PMID 37251321, 2023). "A remarkable attention has been paid to PPARα antagonists, whose activity on fatty acid metabolism could be responsible for a metabolic alteration of cancer cells, by promoting a switching from glycolysis to fatty acid oxidation." (PMID 36674831, 2023). "Inhibition of PPARα in B cells can block the production of tBregs, suggesting that targeting PPARα may be beneficial in the regulation of tBregs-mediated cancer escape." (PMID 37251321, 2023). "Thus, here, we will describe PPARα and PPARγ functions with respect to the hallmarks of cancer and updates for PPARβ/δ." (PMID 35954274, 2022). "Although PPARα agonists have been reported to show antitumor effects in colon carcinogenesis, it is still disputed whether PPARα represses or promotes cancer." (PMID 36355178, 2022). "As several epigenetic repression mechanisms have been shown in rodent cancer models and inflammation, the differences in epigenetic modifications in PPREs may be involved in the regulation of gene repression or activation of PPARα’s target genes." (PMID 36507526, 2022). "In addition to inflammation regulation, PPARα also participates in various pathophysiological processes, including oxidative stress, apoptosis, and even tumorigenesis and cancer progression." (PMID 36014464, 2022). "In conclusion, most of the studies suggest that PPARα activation induces apoptosis in cancer cells." (PMID 35954274, 2022). "Moreover, our observations suggest that the direct inhibition of SLC47A1 (by its knockdown, knockout, or by means of cimetidine) or its indirect inhibition (by the knockdown of PPARA) can sensitize cancer cells to pharmacological ferroptosis induction." (PMID 36575162, 2022).
cancer (continued). "In addition to fatty acid metabolism and inflammation regulation, recent studies have shown that PPARα participates in various pathophysiological processes, including oxidative stress, apoptosis, and even tumorigenesis and cancer progression." (PMID 36014464, 2022). "To investigate whether PPARα activity plays a pathophysiologic role in cancer cachexia in this model, we examined PPARα activity in the liver of mice fed normal chow and the ketone ester diet." (PMID 35719965, 2022). "Several target genes repressed by PPARα are related to cancer progression and tumor growth." (PMID 36507526, 2022). "The LD–PPARα axis was higher in pancreatic and colorectal CSCs than in non-CSCs, and the pharmacological and genetic inhibition of PPARα and its upstream suppressed cancer stemness." (PMID 33466690, 2021). "PPARα promotes ferroptosis by mediating lipid remodeling in cancer cells." (PMID 33928101, 2021). "Additionally, the ClueGO Kyoto Encyclopedia of Genes and Genomes (KEGG)/BioCarta pathway analyses of these DEGs revealed pathways in cancer, and the PPARA and Wnt signaling pathways were most significantly enriched." (PMID 33568630, 2021). "Interestingly, a recent study unveiled that fatty acid-enriched cancer exosomes markedly activate PPARα in tumor-infiltrating dendritic cells, resulting in mitochondrial overdrive and impaired dendritic cell-mediated CD8+ cytotoxic T-cell priming." (PMID 33946986, 2021). "Another interesting example of a negative biomarker (for 11 of the 18 cancer types) was PPARA, which encodes a ligand-activated TF regulating lipid metabolism and fatty acid oxidation." (PMID 34430923, 2021). "Here, we discuss recent advances focused on the PPARα- and PPARγ-related regulation of non-coding RNAs, histone modification, and DNA methylation in the context of cancer and metabolic and immune-related disorders, as well as the emerging therapeutic potential of these processes in these diseases." (PMID 34638914, 2021). "The decrease in expression of PPARα in carcinoma samples in comparison to normal tissue was detected in 15/37 patients (i.e., 40.5%), the increase in 14/37 (37.8%) patients and 8/37 (21.6%) patients samples showed the same staining intensity for normal and tumour tissue samples." (PMID 34572440, 2021). "As such, targeting PPARα can be exploited to improve DC-based cancer therapy." (PMID 33086073, 2020). "PPARα and PPARγ have also been suggested as mediators of the anti-angio- and tumorigenic effects of pomegranate extract as their respective antagonists abolished the beneficial effects of pomegranate extract on cancer vascularization and growth." (PMID 32785018, 2020). "Further investigations are required to figure out the potentials of PPARs and their coactivators as drug targets for cancer, which makes our study even more important in the contribution to the expression signature analysis of PPARA, PPARD, PPARG, PPARGC1A, and PPARGC1B." (PMID 33029111, 2020). "It is reported that PPAR activation might have an effect on the prevention of cell senescence and that PPARα silencing induces cancer cell senescence." (PMID 32041168, 2020). "On the other hand, ATGL may have a broad influence on cancer processes, such as redox homeostasis, inflammation, and autophagy, through PPARα signaling." (PMID 33364199, 2020). "However, in cancer, the functional relationship between FASN and PPARα is controversial and it differs between cancer types." (PMID 32872164, 2020). "In addition to PPARγ, the other PPAR subtypes PPARα and PPARδ have been also reported to play important roles in regulating cancer cell growth." (PMID 33266062, 2020). "Several studies using cancer cell lines have shown PPARα as a biomarker." (PMID 31719612, 2019).
cancer (continued). "Similarly, PPARα serves as E3 ligase to induce Bcl2 ubiquitination and degradation leading to increased cancer cell apoptosis in response to chemotherapeutic agents." (PMID 30519260, 2018). "Our results demonstrated that PPARα induced cancer cell autophagy without effect on autophagy-associated gene expressions." (PMID 30519260, 2018). "Agonist (clofibrate) significantly decreased Bcl2 protein levels and increased autophagy and inhibition of tumor progression in a PPARα-dependent manner, which suggests that PPARα could be a potential drug target for cancer treatment." (PMID 30519260, 2018). "This is further evidence of the ability of PPARα to modulate cancer cell metabolism." (PMID 29966227, 2018). "The three PPAR subtypes, PPARα, PPARγ and PPARβ/δ, are often activated in tumors, where these receptors appear to modulate cell proliferation, differentiation and survival, supporting an important role of PPARs in cancer biology." (PMID 28594934, 2017). "In particular, the PPARα isoform appears to play an important role in the biology of different tumors where it may act as a tumor suppressor or an oncoprotein depending on cancer type." (PMID 28594934, 2017). "5-LO, mPGES1, PPARα, and PPARγ are also potential drug targets for anti-cancer therapies." (PMID 26887049, 2016). "To examine whether cyclin D1 may regulate PPARα-mediated metabolism in malignant cells, we tested a number of different cancer cell lines." (PMID 27351284, 2016). "Thus, the biological function of PPARα in human cancers is still controversial and its role needs further investigation." (PMID 27835866, 2016). "However, in both hepatocytes and the cancer cell lines examined here, cyclin D1 represses PPARα activity and FA oxidation." (PMID 27351284, 2016). "In cancer, PPARα is upregulated at the transcriptional level in response to hypoxia in GBM cells." (PMID 27589734, 2016). "In addition, the rest of 11 TFs such as SAMD4, MYC, PPARG, and PPARA have also been proved to play key roles in various cancer progressions." (PMID 26425543, 2015). "PPARα expression has a major impact on the maintenance of mitochondrial beta-oxidation and has been controversial whether it promotes, or suppresses cancer growth." (PMID 25327562, 2014). "Additionally, proteins that are overexpressed in cancer cells are among the targets of down-regulated miRNAs in different treatment conditions, which includes Wnt3A, PPARα, UCP2, CSF1, and MED1." (PMID 24387052, 2014). "Appropriate stimulation of PPARα suppresses the cancer through the microcirculation." (PMID 23316217, 2012). "This suggests a possibility that neoplastic cells may have greater PPARα/β expression/activity, which should activate genes controlling cellular metabolism and result in faster metabolic rates of cancer cells." (PMID 22448166, 2012). "Nonetheless, the speculations concerning PPARα/β relative expression and function in cancer cells are further based on their opposite to PPARγ physiological roles." (PMID 22448166, 2012). "In brief, HCV core, which can lead to carcinoma, is abnormally sustained by PPARα activation." (PMID 23316217, 2012). "There is also a close relationship of PPARα-induced cancer formation with increased production of ROS due to peroxisome proliferation that might contribute to DNA damage." (PMID 20847941, 2010). "JTT-705 could trigger the p38 MAPK pathway through its interaction with PPARα/γ and thus has the potential to prevent cell proliferation and cancer." (PMID 19436720, 2009). "Thus, we dedicate the next section to articles that review preclinical and clinical studies of the use of PPARα and PPARγ ligands in a variety of cancer models, including combinatorial therapy." (PMID 19590598, 2008). "In extrahepatic tissues, there have been fewer studies regarding PPARα and cancer.Initially, it was suggested that PPARα may preventskin cancer." (PMID 19043612, 2008). "Activation of PPARα in cancer cells inhibits proliferation andsuppresses metastatic potential." (PMID 18551186, 2008).
cancer (continued). "Interestingly, there is aninverse relationship between mean PPARα and ERα mRNA levels in ER-positivebreast cancer cells." (PMID 18645617, 2008). "The involvement of PPARα and PPARγ in cancer pathogenesishas been reviewed extensively." (PMID 19197366, 2008). "The prediction would be that in the rat urothelium in vivo, PPARα activation may providecancer initiation and PPARγ activation cancer promotion signals." (PMID 19197366, 2008). "Itis, therefore, clear that the regulation of angiogenic factors by PPARα and PPARγ may bedetermined by cell and cancer type and the experimental models used." (PMID 19043612, 2008). "Studies concerning PPARα activation inbreast carcinomas are scarce." (PMID 18645617, 2008). "Interestingly, prolonged exposure to WY14643 in these miceonly led to a 5% incidence of liver tumors—includinghepatocellular carcinoma—compared to the71% observed in mice expressing the mouse PPARα." (PMID 18725983, 2008). "Additionally, we conducted indirect coculture experiments to confirm whether inhibiting the CCL2/CCR2/PPARα axis in ADSCs affects cancer cell proliferation." (PMID 41160815, 2026). "Normal B and cancer 1 clusters shared inflammatory markers CCL2, TNFRSF12A, and IL1R1, pathways including TNFα, IL, and Myc signaling, and activity of inflammation, hypoxia, and lipid metabolism–associated transcription factors NFATC2, ARNT, PPARA, and PPARGC1A." (PMID 40215177, 2025). "Nevertheless, some evidence suggests that PPARα may also exert a pro-cancer effect." (PMID 39875357, 2025). "Similarly, PPARα plays a crucial role in cancer lipid metabolism reprogramming by promoting FAO." (PMID 41345744, 2025). "Thus, it increased lipid formation and storage in cancer cells via PPARα and PPARβ/δ." (PMID 38674023, 2024). "TPST-1120 is a first-in-class oral inhibitor of peroxisome proliferator-activated receptor α (PPARα), a fatty acid ligand-activated transcription factor that regulates genes involved in fatty acid oxidation, angiogenesis, and inflammation, and is a novel target for cancer therapy." (PMID 38551394, 2024). "Several studies demonstrated that both PPARα and PPARγ could be involved in cancer apoptosis." (PMID 37237519, 2023). "Similarly, PPARα activation suppressed HIF-1 signalling in cancer cells." (PMID 36429023, 2022). "Thus far, our study suggests that cancer stemness is maintained through activation of the PPARα." (PMID 33466690, 2021). "Therefore, PPARα is necessary for the maintenance of cancer stemness." (PMID 33466690, 2021). "Additionally, the emergence of next-generation PPAR modulators, such as the selective PPARα modulator, pemafibrate, and dual- and pan-PPAR agonists such as saroglitazar, elafibranor, lanifibranor, and chiglitazar, brings about new prospects to PPAR cancer research." (PMID 33946986, 2021). "However, it is still controversial whether the roles of PPARα is cancer-repressing or cancer-promoting." (PMID 33029111, 2020). "However, whether it has any advantages in the treatment of cancer in comparison to other traditional PPARα agonists is still unknown." (PMID 31791289, 2019). "We hypothesize that upregulation of TFEB, PGC1α and PPARα as well as increasing lipid uptake via CD36 as discovered in our study is an escape mechanism, by which the cancer cells try to compensate for defective mitochondria and loss of energy induced by V-ATPase inhibition." (PMID 31358011, 2019). "The cancer risk assessments conducted by many different regulatory authorities have changed over time with the advent of detailed mechanistic information on the involvement of PPARα in the non-genotoxic carcinogenic process, in which metabolites of DEHP activate PPARα signaling." (PMID 31279339, 2019). "Therefore, PPARα is a promising therapeutic target for cancer." (PMID 31775380, 2019). "Therefore, PPARα is a promising target for the treatment of cancer." (PMID 31775380, 2019). "Moreover, PPARα agonist increased SW480 cancer cell chemotherapy sensitivity." (PMID 30519260, 2018).
cancer (continued). "However, the effect of PPARα on cancer cell autophagy is still unclear." (PMID 30519260, 2018). "Other reports show that ligand-activated PPARα increases autophagy of AML12 cells or livers via PPARα-mediated autophagy-associated gene expressions, while here we found that PPARα induced cancer cell autophagy independent of its transcription activity by release of Beclin-1/VPS34 complex." (PMID 30519260, 2018). "We next assessed whether activation of PPARα influenced cancer cell migration." (PMID 26869356, 2016). "Importantly, overexpression of PPARα enhanced cancer cell chemotherapy sensitivity." (PMID 26556865, 2015). "Based in the limited work performed on PPAR ubiquitination (as recently reviewed), we hypothesized that the ratio of MuRF2 to the substrate may regulate whether the protein was degraded in a proteasome-dependent manner, as previously reported in cancer with MDM2:PPARα ratios." (PMID 26242235, 2015). "PPARα is a nuclear receptor protein that functions as a transcription factor for genes including those encoding enzymes involved in energy metabolism; while PPARα has been reported to regulate tumor growth in several cancers, it has not been evaluated in RCC." (PMID 23951092, 2013). "Whether this finding is due to causality of PPARα activation in oncogenesis or whether it is simply a cancer “signature” was not determined in that study." (PMID 23951092, 2013). "However, the chronic administration of PPAR agonists in human for the treatment of metabolic diseases may importantly increase the risk of developing cardiovascular diseases (e.g., for PPARγ agonists) and specific cancers (e.g., for PPARα agonists)." (PMID 23024649, 2012). "In respect to the anti-cancer properties of fenofibrate, activated PPARα, which is a transcriptional activator of the fatty acid β-oxidation machinery, could switch energy metabolism towards fatty acid degradation, and decrease glucose uptake by repressing glucose transporter GLUT4." (PMID 20569465, 2010). "Takentogether, findings on the effects of PPARα ligands in inflammation and cancer, suggestthat PPARα activation may be beneficial againsttumorigenesis through the inhibition of transcriptional activation of genesinvolved in inflammation and angiogenesis such as COX-2 and VEGF." (PMID 18670614, 2008). "Much as cancer research was initially focused on the tumor parenchyma, the first connection between PPARα and tumorigenesis was also directed at understanding how prolonged PPARα activation by its ligands induces hepatocarcinogenesis in rodents by altering liver cell function." (PMID 19590598, 2008). "Thus, targeting PPARα may prove to be a potential therapeuticstrategy—either alone orin combination with conventional chemotherapy—to inhibit andideally prevent cancer with excellent tolerance and limited toxicity." (PMID 18725983, 2008). "Cancer cells drive adjacent adipose tissue to release fatty acids by secreting CCL2, which activates PPARα‐dependent lipolysis." (PMID 41160815, 2026). "This study demonstrated that ether-lipids accelerate cancer cell mobility through TRPV2 activation and that pathological PPARα downregulation compromised ether-lipid clearance in HCC, posing significant challenges to cancer prognosis." (PMID 40936093, 2025). "The PI3K/AKT/mTOR pathway is activated by CD147 to up-regulate HIF-1α-mediated glycolysis, and CD147 inhibits PPARα-mediated FAO by activating the MAPK pathway, which eventually leads to drug resistance in cancer cells." (PMID 40514365, 2025). "Specifically, PPARα induces FAO-related gene expression, facilitating FFA breakdown to generate energy for cancer cells." (PMID 41345744, 2025). "PPARα agonists also decreased the PPARα/Sp1-dependent expression of KDR and Cyp7b1 and induced pl6NK4a in non-cancer cell lines." (PMID 39858066, 2025).